OR1E1 (olfactory receptor family 1 subfamily E member 1)
Description:
Odorant receptor.
Synonyms: OR13-66; OR17-2; OR17-32; OR1E5; OR1E6; OR1E9P; HGM071; OR1E8P; OST547
Tractability: Antibody: its Gene Ontology location is reachable by antibodies, with high confidence; UniProt places it where antibodies can reach, with medium confidence; UniProt predicts a signal peptide or a membrane-spanning region.
Gene: Protein-coding gene on chromosome 17 (3,397,104 to 3,398,410, reverse strand). Ensembl gene ENSG00000180016.
Subcellular location: Cell membrane
Pathways (Reactome):
Sensory Perception: Expression and translocation of olfactory receptors; Olfactory Signaling Pathway
Gene Ontology:
Molecular function: olfactory receptor activity; G protein-coupled receptor activity; signaling receptor activity
Biological process: sensory perception of smell; signal transduction; detection of chemical stimulus involved in sensory perception of smell; G protein-coupled receptor signaling pathway; sensory perception of chemical stimulus
Cellular component: plasma membrane; membrane
Genetic constraint (gnomAD): Missense variants: 263 observed, 317.88 expected, observed/expected ratio (o/e) 0.83, 90% interval 0.75 to 0.92. Synonymous variants: 102 observed, 130.8 expected, observed/expected ratio (o/e) 0.78, 90% interval 0.66 to 0.92.
Homologues: Orthologues: chimpanzee OR1E1 (98% identical), macaque OR1E1 (94% identical). Paralogues in human: OR1E2 (95% identical), OR1J4 (61% identical), OR1J2 (60% identical), OR1J1 (57% identical), OR1F1 (56% identical), OR1N2 (56% identical), OR1N1 (55% identical), OR1G1 (55% identical), OR7C1 (55% identical), OR7C2 (54% identical), OR1M1 (54% identical), OR7D2 (54% identical), and 116 more.
Diseases named in the same sentence as OR1E1 in open-access papers:
OR1E1 is named in the same sentence as 1 disease in open-access papers, as found by Europe PMC text mining. Sharing a sentence is not in itself a finding about the gene and the disease.
OR1E1 shares sentences with these, for which no sentence is quoted: breast carcinoma (1 paper).